TLR4 (toll like receptor 4)
Diseases named in the same sentence as TLR4 in open-access papers (continued):
Sharing a sentence is not in itself a finding about the gene and the disease.
autoimmune glomerulonephritis (3 papers, 2012 to 2022). An autoimmune form of glomerulonephritis (disease). "For instance, increased TLR4 causes lupus-like disease and autoimmune glomerulonephritis." (PMID 35796625, 2022).
avian influenza (3 papers, 2009 to 2016). Infection of domestic and wild fowl and other birds with influenza A virus. "Indicating a role of DAMPs in virus sensing, TLR4-deficient mice were found to be resistant to avian influenza-induced death during H5N1 avian influenza infection mediated by TLR4 recognition of cell-released oxidized phospholipids." (PMID 23435233, 2013). "More recently, TLR-4 was shown to be upregulated in mice with acid-induced or inactivated avian influenza-induced lung injuries; and TLR-4 deficient mice showed less severe acute lung injuries to these challenges." (PMID 19505311, 2009). "In previous studies with other viruses such as highly pathogenic avian influenza (HPAI), TLR-4 agonist adjuvants have been shown to increase protection not only to homologous virus, but also to antigenically distinct heterologous viruses." (PMID 26901122, 2016).
cervical intraepithelial neoplasia (3 papers, 2017 to 2025). "We found that the rs4986790 (NcoI) polymorphism in TLR-4 was significantly associated with an increased risk of cervical dysplasia." (PMID 41374999, 2025). "The primary goal of this study was to investigate the association between SNPs in TLR-4 and TLR-9 with cervical dysplasia severity and HPV infection." (PMID 41374999, 2025). "This study provides the first evidence of an association between specific SNPs in TLR4 and TLR9 and the severity of cervical dysplasia and HR-HPV infection in a cohort of Hispanic women from Puerto Rico." (PMID 41374999, 2025). "Our study provides novel evidence that specific SNPs in TLR4 and TLR9 are associated with an increased risk of cervical dysplasia and HR-HPV infection in our patients." (PMID 41374999, 2025). "This study evaluated the presence of single-nucleotide polymorphisms (SNPs) in Toll-like receptors (TLR4 and TLR9) among women with cervical dysplasia and HPV infection, as potential immune-related susceptibility factors." (PMID 41374999, 2025).
cervicitis (3 papers, 2019 to 2024). An acute or chronic inflammatory process that affects the cervix. "On comparing TV infected cervicitis patients to controls, a higher frequency of CC genotype (age-adjusted OR, 2.216 [95% CI, 1.076 to 4.560]; p = 0.031) of TLR4 rs11536889 polymorphism was found among TV positive cases as compared to controls." (PMID 31365550, 2019). "Coming back to pathogen infection and TLR polymorphisms, we found TLR4 rs11536889 CC genotype to be significantly associated with higher risk of TV induced cervicitis." (PMID 31365550, 2019). "Furthermore, as compared to controls, the rs11536889 C (TLR4) allele was found to increase the risk of cervicitis." (PMID 37937275, 2023). "In addition, TLR4 rs11536889 C allele was shown to increase the risk of cervicitis (age-adjusted OR, 1.632 [95% CI, 1.132 to 2.352]; p = 0.009) compared to controls." (PMID 31365550, 2019). "TLR4 haplotype GCA and TLR9 haplotype GTA were associated with a lower and higher risk of cervicitis." (PMID 37937275, 2023). "Based on our results, we suggest a significant influence of TLR4 and TLR9 polymorphisms on cervicitis." (PMID 31365550, 2019). "Ten single nucleotide polymorphisms, five each of TLR4 and TLR9 genes were analyzed among 130 cervicitis patients and 150 controls either using polymerase chain reaction-restriction fragment length polymorphism or allele specific-PCR." (PMID 31365550, 2019). "Genotype and allele frequency distribution of TLR4 and TLR9 gene polymorphisms in cervicitis and control subjects." (PMID 31365550, 2019). "The cervicitis patients were less likely to carry TLR4 rs10759931 AG genotype as compared to control population (age-adjusted OR, 0.418 [95% CI, 0.220–0.794]; p = 0.008)." (PMID 31365550, 2019). "The TLR4 and TLR9 SNPs as well as haplotypes modulated the cervicitis risk as a whole and TV induced cervicitis as well." (PMID 31365550, 2019). "We found TLR4 3′ UTR rs11536889 CC genotype and C allele to be associated with increased the risk of cervicitis." (PMID 31365550, 2019). "TLR4 GCA and TLR9 GTA haplotypes were significantly associated with decreased and increased risk of cervicitis respectively." (PMID 31365550, 2019). "On the other hand TLR4 rs10759931 AG genotype showed a protective effect against cervicitis in our study subjects." (PMID 31365550, 2019). "The TLR4 haplotype GCA (OR, 0.6 [95% CI, 0.38–0.95]; p = 0.0272) and TLR9 haplotype GTA (OR, 1.99 [95% CI, 1.14–3.48]; p = 0.014) were found to be associated with decreased and increased risk of cervicitis respectively." (PMID 31365550, 2019). "TLR4 and TLR9 polymorphisms, as well as haplotypes were shown to modulate the cervicitis risk." (PMID 31365550, 2019). "The damage-associated proteins (DAMPs) generated from NETs, such as citrullinated histones H3 [H3Cit] or myeloperoxidase (MPO), may interact with Toll-like receptor 4 (TLR-4) and may contribute to the maintenance of cervical inflammation and blood-brain barrier damage." (PMID 38241272, 2024). "The rs11536889 CC (TLR4) and rs187084 TC (TLR9) genotypes had a larger distribution in cervicitis patients than in controls." (PMID 37937275, 2023). "TLR4 rs11536889 CC (age-adjusted OR, 2.469 [95% CI, 1.499 to 4.065]; p < 0.001) and TLR9 rs187084 TC (age-adjusted OR, 2.165 [95% CI, 1.267–3.699]; p = 0.005) genotypes showed the higher distribution in cervicitis patients compared to controls." (PMID 31365550, 2019).
chronic asthma (3 papers, 2022 to 2023). An asthma that is characterized by the development of persistent airway inflammation and recurrent attacks of breathlessness and wheezing, which vary in severity and frequency. "Collectively, these data further support the notion that inhibition of the TLR4/NF-κB signaling pathway by DEX has a protective role in the chronic asthma model." (PMID 36846195, 2023). "To confirm the possible mechanism of DEX in protecting against chronic asthma, we explored the activation of the TLR4/NF-κB signaling pathway after DEX intervention." (PMID 36846195, 2023). "Inhibition of TLR4 signaling showed positive effects in a murine chronic asthma model through hampering of the Th2 response and suppression of airway remodeling." (PMID 36678520, 2022). "TLR4 was confirmed as a therapeutic target in the management of airway remodeling in house dust mite-induced chronic asthma." (PMID 36678520, 2022).
Coagulopathy (3 papers, 2020 to 2025). "Additionally, increased coagulopathy was associated with platelet-TLR4 and leukocyte-TLR10." (PMID 40825056, 2025). "Coagulopathy, measured by INR, was associated with platelet-TLR4 and leukocyte-TLR10." (PMID 40825056, 2025). "Additionally, coagulopathy measured by INR, negatively correlated with TLR4 in platelets and TLR10 in leukocytes." (PMID 40825056, 2025).
cognitive (3 papers, 2020 to 2025). "To explore the role of TLR4 in the course of B2M-induced cognition impairment, we measured TLR4 mRNA expression in the hippocampus of the WT mice from Veh group and B2M group on day 7 and 28 after B2M treated." (PMID 32059688, 2020). "TLB:Improves cognitive deficits in both animal models.Ameliorates neuroinflammation and oxidative stress by inhibiting the HMGB1/TLR4/NF-κB signaling pathway and activating the SIRT3/SOD2 pathway, which helps to restore redox homeostasis and suppress neuroinflammation." (PMID 39459209, 2024).
crescentic glomerulonephritis (3 papers, 2020 to 2022). A histopathologic term for a pattern of diseases characterized by extensive crescent formation in the glomeruli; patients present clinically with rapid deterioration of renal function, and possible progression to end-stage renal failure within weeks or months. "Previously, this study demonstrates the critical role of myeloid specific TLR4 in macrophage‐mediated progressive renal injury in anti‐glomerular basement membrane (anti‐GBM) crescentic glomerulonephritis (cGN); however, the underlying mechanism remains largely unknown." (PMID 35484716, 2022). "In this study, the authors discover that deletion of myeloid TLR4 inhibits immunologically mediated crescentic glomerulonephritis (cGN) by inducing a novel Nr4a1/Ear2‐expressing anti‐inflammatory macrophages while suppressing M1 proinflammatory responses." (PMID 35484716, 2022). "TLR2 promotes crescentic glomerulonephritis, whereas TLR4 promotes inflammation associated with ischemic AKI in diabetic mice, which can be rescued by the TLR4 specific inhibitor CRX-526." (PMID 32512831, 2020). "To uncover the hypothetical TLR4‐dependent regulation on macrophage/monocytes differentiation in crescentic glomerulonephritis, we re‐clustered these populations (Cluster 0, 1, 3, 4, 7, 8, and 9) to construct single cell–based differentiation trajectory in our scRNA‐seq data." (PMID 35484716, 2022).
delirium (3 papers, 2022 to 2025). A disorder characterized by confusion; inattentiveness; disorientation; illusions; hallucinations; agitation; and in some instances autonomic nervous system overactivity. "Levels >2 mmol/L promote delirium via three pathways: 1) astrocytic glutamate uptake inhibition (excitotoxicity); 2) microglial TLR4/NF-κB pathway activation (neuroinflammation); 3) cerebral acidosis impairing neurotransmitter dynamics." (PMID 40727448, 2025). "Inhibiting TLR4/NF-κB/MAGI-2 signaling pathway could reduce postoperative delirium." (PMID 35294925, 2022). "Dexmedetomidine’s delirium-sparing effects in AKI may also be related to its hepatic clearance, and potential renoprotective effects via stabilization of the sympathetic system, and anti-inflammatory toll-like receptor-4-mediated effects." (PMID 36030220, 2022).
dental caries (3 papers, 2018 to 2024). The decay of a tooth, in which it becomes softened, discolored, and/or porous. "The aim of the present study was to analyze the association of the TLR2 2258G>A (rs5743708), TLR4 896A>G (rs4986790), and TLR4 1196C>T (rs4986791) polymorphisms with dental caries in Polish children." (PMID 39000094, 2024). "It is also recommended to conduct studies analyzing the role of TLR2 and TLR4 gene–environment interactions in dental caries susceptibility." (PMID 39000094, 2024). "However, further studies conducted in other populations/ethnic groups examining other SNPs are needed to test the consistency of our findings in order to draw definitive, final conclusions regarding the association between TLR2 and TLR4 SNPs and dental caries." (PMID 39000094, 2024). "The aim of the present study was to analyze the association of the TLR2 (Toll-like receptor 2 gene) 2258G>A (rs5743708), TLR4 (Toll-like receptor 4 gene) 896A>G (rs4986790), and TLR4 1196C>T (rs4986791) polymorphisms with dental caries in Polish children." (PMID 39000094, 2024). "We found a lack of association of alleles, genotypes of TLR2 and TLR4 SNPs, and TLR4 haplotypes with dental caries in Polish children, suggesting that these gene variants do not affect the caries risk (susceptibility)." (PMID 39000094, 2024). "Finally, TLR2 and TLR4 expressions in the dental pulp has been studied using a murine dental caries model." (PMID 30631444, 2018). "We hypothesize that genetic variants of TLR2 and TLR4 that might potentially influence the TLR2 and TLR4 receptor expression and/or function lead to alterations in cariogenic bacteria recognition, binding, and biofilm formation, thus affecting dental caries susceptibility." (PMID 39000094, 2024).
dermatophytosis (3 papers, 2018 to 2023). A common fungal infection of the stratum corneum of the skin, hair, or nails by a dermatophyte. "In this study, we aimed to investigate the expression of TLR‐2 and TLR‐4 in feline dermatophytosis lesions and clear the importance of these receptors in host immune response by the recognition of dermatophytes." (PMID 36913145, 2023). "Increased expression of TLR‐2 and TLR‐4 mRNAs in cat skin biopsies suggests that these receptors are involved in the immune response by recognizing dermatophytosis." (PMID 36913145, 2023). "It is the first time that feline skin biopsies are clinically examined for TLR‐2 and TLR‐4 gene expression in animal dermatophytosis." (PMID 36913145, 2023). "Interestingly, reduced expression of TLR4 in patients with disseminated dermatophytosis was found compared to that in healthy controls, indicating that the lack of TLR4 might contribute to the lack of infection resolution and the resulting chronic state of dermatophytosis." (PMID 38022599, 2023). "(2015) described that the expression of TLR‐4 (but not of TLR‐2) was decreased in lesions of patients with disseminated dermatophytosis, which indicates the possible mechanism for the chronicity of dermatophytosis." (PMID 36913145, 2023).
dilatation (3 papers, 2011 to 2021). "Further functional studies are necessary to elucidate the combined role of TLR4 and MMP9 in AAA development and to address its possible interest as a prognostic or therapeutic target in aneurysmal disease." (PMID 34348653, 2021).
disc degeneration (3 papers, 2020 to 2025). "In addition to OA, TLR4 is implicated in other musculoskeletal diseases, such as inflammatory arthritis, disc degeneration, and peripheral neuropathy." (PMID 33060735, 2020). "Silencing TLR4 using small interfering RNA (siRNA) in NP cells has been shown to reduce proinflammatory cytokine expression and apoptosis, while in vivo inhibition of TLR4 attenuates disc degeneration in rodent models." (PMID 40564831, 2025).
disseminated candidiasis (3 papers, 2007 to 2021). Systemic candidiasis occurs when Candida yeast enters the bloodstream and may spread (becoming disseminated candidiasis) to other organs, including the central nervous system, kidneys, liver, bones, muscles, joints, spleen, or eyes. "Netea demonstrated that the absence of TLR4-mediated signals resulted in an increased susceptibility to disseminated candidiasis in TLR4-defective mice." (PMID 17982419, 2007). "Lack of TLR4 and TLR2 responses were shown to affect disseminated candidiasis in mice: lack of TLR4 caused an increased C. albicans kidney burden, while blocking of TLR2 inhibited the production of inflammatory cytokines such as tumor necrosis factor alpha (TNF-α) and IL-1β." (PMID 33526565, 2021).
Dyskinesia (3 papers, 2022 to 2024). A movement disorder which consists of effects including diminished voluntary movements and the presence of involuntary movements. "Studies have reported decreased AP-1 expression in dopaminergic neurons, less reduction in ROS content, and improved dyskinesia in PD mice in the MPTP model of TLR4-knockout (KO) mice, suggesting that TLR4 plays a key role in the pathogenesis of PD." (PMID 38356648, 2024).
dyslipidaemia (3 papers, 2019 to 2024). "It should be acknowledged that TLR2 and TLR4 stimulants are well-established to trigger systemic inflammation and dyslipidaemia when delivered at high doses intravenously." (PMID 31316501, 2019). "Dyslipidaemia can enhance the CXCR3+ follicular T helper cell (TFH cell) response and promote immunoglobulin IgG2c production in a manner dependent on Toll-like receptor 4 (TLR4) and the cytokine IL-27 in the SLE mouse model." (PMID 33897433, 2021).
eating disorder (3 papers, 2016 to 2024). A broad group of psychological disorders with abnormal eating behaviors leading to physiological effects from overeating or insufficient food intake. "Our observations significantly add to the emerging role of intestinal TLRs in eating disorders, suggesting that the TLR4 pathway may thus have a dual role, both pathogenic and protective." (PMID 27779218, 2016). "Although TLR4 expression in CNS plays an important role in eating disorder, the TLR4 in periphery still affects the process of appetite." (PMID 34899611, 2021).
Ebola (3 papers, 2018 to 2022). "For instance, they recently showed for the first time that despite the incapability of Ebola to infect lymphocytes, it directly binds to them, involves the TLR4 pathway, and causes cell death." (PMID 35275959, 2022). "The synthetic TLR4 agonist glucopyranosyl lipid A (GLA-SE) as an adjuvant increased the protection provided by the inactivated RABV-based Ebola vaccine." (PMID 31816996, 2019). "The results demonstrated that adding a chemical that blocks TLR4 activation could protect the lymphocytes in the presence of Ebola." (PMID 35275959, 2022). "This could lead to design a drug that blocks TLR4 and might be used to treat patients with Ebola." (PMID 35275959, 2022). "We verified that indeed in our primary NKs, TLR4 is not expressed on the cell membrane, and thus TLR4 cannot contribute to recognition of Ebola GP by NK." (PMID 30013549, 2018).
edema (3 papers, 2013 to 2015). An abnormal accumulation of fluid beneath the skin, or in one or more cavities of the body. "Activation of TLR-4 has been assigned a prominent role in adult ICH as a mediator of pro-inflammation, cerebral edema and neurological deficit." (PMID 23915174, 2013). "Our previous research demonstrated that, following brain ischemic injury, picroside II can remove free radicals, has antioxidant properties, decreases MMP-9 expression and inhibits the toll-like receptor 4 and nuclear factor kappa B (TLR4-NFκB) signaling pathways to relieve cerebral edema." (PMID 25927985, 2015).
epididymitis (3 papers, 2018 to 2023). Inflammation of the epididymis. "The first demonstration that TLR4 activation by LPS was sufficient to elicit epididymitis came from a rat model of experimentally induced systemic endotoxemia." (PMID 33329594, 2020). "Lipopolysaccharide-induced epididymitis is a well-established mouse model of epididymitis used for investigating the pathogenic mechanism involved in the role of the Toll-like receptor 4 (TLR4) as the outer membrane of Gram-negative bacteria such as E. coli and the agonist of TLR4." (PMID 37175545, 2023). "Thus, the harmful effects of LPS-induced epididymitis on epididymal sperm parameters could be due to both direct cytotoxic effects of LPS on spermatozoa through TLR4-dependent pathways and/or indirectly via cytokine secretion and ROS production by the immune and non-immune cells of the epididymis." (PMID 29311626, 2018).
falciparum malaria (3 papers, 2013 to 2024). "In the assessment of the two TLR4 polymorphismsin the co-segregate state, we found that thefrequency of different TLR4 co-segregating genotypeswas not significantly different among Baluchipatients infected with mild falciparum malaria andBaluchi healthy individuals (p>0.05)." (PMID 23862121, 2013).
fetal growth restriction (3 papers, 2019 to 2025). A fetus that does not grow beyond the 10th percentile of conventionally accepted weight for gestational age. "Fetal growth restriction in TLR4 deficient mothers was accompanied by an increase in placental size, and a decrease in fetal to placental weight ratio." (PMID 34400677, 2021). "It was suggested that the effect of intrauterine growth restriction on hepatic TLR4 expression may be due to the dysregulation of baseline cytokine expression in the liver." (PMID 31011422, 2019).